LCP1 (lymphocyte cytosolic protein 1)
Diseases named in the same sentence as LCP1 in open-access papers (continued):
Sharing a sentence is not in itself a finding about the gene and the disease.
Stroke (3 papers, 2024 to 2025). Sudden impairment of blood flow to a part of the brain due to occlusion or rupture of an artery to the brain. "Combining in vitro and in vivo studies with comprehensive bioinformatics analysis using single-cell RNA sequencing data, and the high-dimensional CyTOF technique for protein activation analysis, we aim to unveil the underlying mechanisms of LCP1 modulation of lipid metabolism in relation to stroke." (PMID 38164159, 2024). "By targeting LCP1 and its associated metabolic pathways, it may be possible to restore immune cell function, improve immune responses, and mitigate the risk of infections in stroke patients." (PMID 38164159, 2024). "Lymphocyte Cytosolic Protein 1 (LCP1), a protein found in immune cells 35, is a promising stroke therapy candidate." (PMID 38164159, 2024). "Understanding the role of LCP1 in macrophage metabolism during stroke could provide insights into stroke treatment, as previous studies have shown LCP1's potential to influence cellular metabolic processes and immune responses." (PMID 38164159, 2024). "We hypothesize that LCP1 influences macrophage metabolism, particularly glycolysis and lipid metabolism, and thereby affecting stroke outcomes." (PMID 38164159, 2024). "In light of these insights, the present study aims to elucidate the role of LCP1 in stroke outcomes, including both brain injury and immunodepression, and the associated pathological mechanisms, specifically focusing on its impact on lipid metabolism within macrophages." (PMID 38164159, 2024).
autoimmune disease (2 papers, 2014 to 2018). A disorder resulting from loss of function or tissue destruction of an organ or multiple organs, arising from humoral or cellular immune responses of the individual to their own tissue constituents. "COL6A1 has previously been linked to muscle regeneration and associated with other myopathies, whereas LCP1 is a bundle protein linking actin filaments together and associated with autoimmune disease." (PMID 24920607, 2014). "Coincidently, vimentin and other proteins specifically upregulated at day 1 pi with E75CV1, such as HSPB1, enolase or LCP-1, share both their potential role in immune defense and their description as autoantigens in autoimmune disorders." (PMID 30208957, 2018).
breast tumors (2 papers, 2018 to 2019). "LCP1 is inversely correlated with miR-96 expression in breast tumors, suggesting LCP1’s role as a tumor-associated gene that is regulated by miR-96." (PMID 31007850, 2019). "However, LCP1 expression levels significantly increase in breast tumors, are directly correlated with tumor severity and lymph node micrometastases presence." (PMID 31007850, 2019).
glioma (2 papers, 2020 to 2025). A benign or malignant brain and spinal cord tumor that arises from glial cells (astrocytes, oligodendrocytes, ependymal cells). "Out of the well-predicted genes, CDK4, MMP7, MYCBP, and TMEM59 in gliomas and LCP1 in RCC have been implicated in multiple cancer types." (PMID 32194984, 2020). "Western blot analysis confirmed that shLCP1 effectively reduced LCP1 protein levels in both glioma cell lines." (PMID 40740857, 2025). "In the present study, we found that LCP1 promotes cell proliferation and invasion while inhibiting apoptosis in glioma cells." (PMID 40740857, 2025). "In vitro data demonstrated that LCP1 knockdown suppressed cell proliferation and invasion, and promoted apoptosis in glioma cells." (PMID 40740857, 2025). "To explore the role of LCP1 in glioma, we transfected U251 and LN229 cells with shLCP1 to knock down the expression of LCP1." (PMID 40740857, 2025). "Besides LCP1, other 16 LRGs such as LGALS1 and RPL29 should be validated in glioma progression in future studies This study has several limitations that should be acknowledged." (PMID 40740857, 2025).
ischemic stroke (2 papers, 2024). A stroke disorder caused by obstruction of blood flow to the brain, due to thrombotic (local blood clot formation) or embolic (due to a blood clot or other material traveling from another site) event. "In summary, our study provides important insights into the role of LCP1 in ischemic stroke and its potential implications for therapeutic interventions." (PMID 38164159, 2024). "Our research found that there is a previously unrecognized role and dynamic expression between Ccl3 and Lcp1 in basophils in the context of ischemic stroke, providing a new perspective for the synthesis of pathophysiological networks." (PMID 39931101, 2024). "Furthermore, our findings link LCP1 expression to the enrichment of oxidative phosphorylation, ATP biosynthesis, and migration pathways, which may further guide research in dissecting the molecular mechanisms underlying ischemic stroke." (PMID 38164159, 2024). "This may shed light on potential therapeutic strategies for ischemic stroke and underscore the potential of LCP1 as a novel therapeutic target." (PMID 38164159, 2024). "Thus, the study refines our understanding of LCP1's intricate roles in ischemic stroke and sets the stage for future investigations." (PMID 38164159, 2024). "A decrease was particularly noticeable in MoDMs, but not in MiDMs in the LCP1 knockdown mice compared with the control group, corroborating our findings that reduction of LCP1 in MoDMs notably attenuates acute experimental ischemic stroke." (PMID 38164159, 2024).
ovarian carcinoma (2 papers, 2016 to 2024). A malignant neoplasm originating from the surface ovarian epithelium. "In addition, conducting relevant experiments with tissues from ovarian cancer patients who underwent surgery to explore whether high LCP1 expression is associated with poor survival or increased risk of recurrence is crucial for future studies." (PMID 39588922, 2024). "LCP1 is overexpressed in olaparib-resistant ovarian cancer cells, and downregulation of LCP1 can increase olaparib-induced apoptotic cell death and the sensitivity of ovarian cancer to olaparib." (PMID 39588922, 2024). "First, we overexpressed LCP1 in olaparib-resistant ovarian cancer cells and then conducted relevant experiments to explore its relationship with olaparib resistance." (PMID 39588922, 2024). "The LCP1/JAK2/STAT3 axis is a key signaling pathway involved in olaparib resistance in ovarian cancer." (PMID 39588922, 2024). "We demonstrated that LCP1 can promote EMT by activating the JAK2/STAT3 signaling pathway in ovarian cancer cells, thereby promoting tumor cell metastasis and invasion." (PMID 39588922, 2024). "Consistently, overexpression of LCP1 increased the ovarian cancer cell survival rate in the presence of the same concentration of olaparib." (PMID 39588922, 2024). "Based on these findings, we can conclude that LCP1 promotes the metastasis of ovarian cancer cells by activating EMT." (PMID 39588922, 2024). "In summary, in this study, we demonstrated that LCP1 is involved in olaparib resistance in ovarian cancer cells by activating the JAK2/STAT3 pathway and EMT." (PMID 39588922, 2024). "To determine whether LCP1 expression is involved in the resistance of ovarian cancer cells to olaparib, we constructed cell lines with LCP1 knockdown or overexpressing." (PMID 39588922, 2024). "Moreover, the results of flow cytometry showed that overexpression of LCP1 could reduce the apoptosis of ovarian cancer cells induced by olaparib." (PMID 39588922, 2024).
triple-negative breast carcinoma (2 papers, 2024 to 2025). An invasive breast carcinoma which is negative for expression of estrogen receptor (ER), progesterone receptor (PR), and human epidermal growth factor receptor 2 (HER2). "Moreover, LCP1 has been linked to immune cell infiltration and inflammatory signaling in various cancers, including triple-negative breast cancer, and ischemic brain injury, where it modulates macrophage function and cytokine production." (PMID 41044643, 2025). "Ectopic expression of LCP1 has been reported in various solid tumors, including colon, stomach, prostate, and triple-negative breast cancers, where it promotes cell migration, invasion, and metastasis." (PMID 41044643, 2025).
Arthritis (1 paper, 2021). Inflammation of a joint. "Inactivation of LCP1 by antileukoproteinase treatment reduced the frequency and severity of the anti-collagen-II-induced arthritis in mice and has a protective effect against pannus formation and bone erosion." (PMID 35008858, 2021).
asthma (1 paper, 2023). "CXCL10 was upregulated in asthma and LCP1, CCR1, PRKCB, IRAK2, LILRA1, and ZEB1 were significantly upregulated in COPD patients." (PMID 36829591, 2023).
chondrosarcoma (1 paper, 2024). A malignant cartilaginous matrix-producing mesenchymal neoplasm arising from the bone and soft tissue. "In particular low LCP1 mRNA levels are associated with significantly better OS in chondrosarcoma patients (bioRxiv 2023:2023.01.31.526513)." (PMID 38810090, 2024).
head and neck squamous cell carcinoma (1 paper, 2019). A squamous cell carcinoma that arises from any of the following anatomic sites: lip and oral cavity, nasal cavity, paranasal sinuses, pharynx, larynx, and salivary glands. "Here, the same tendency in expression changes of TGM2, MMP2, CLDN7, HOXB7, and LCP1 can be found in different cancer types, including cervical and head and neck squamous cell carcinoma." (PMID 30918060, 2019).
infertile (1 paper, 2022). "The expression of LCP1, CTSH, BPIFB1 and Quiescin sulfhydryl oxidase 1 (QSOX1) is significantly higher in infertile receptive phase uterine lavage compared to fertile." (PMID 36589798, 2022).
invasive carcinoma (1 paper, 2017). A carcinoma that is not confined to the epithelium, and has spread to the surrounding stroma. "Moreover, it is worthy to note that invasive carcinoma cells displayed strong immunoreaction for both LCP1 and F-actin." (PMID 28230172, 2017).
liver cirrhosis (1 paper, 2023). "LCP-1 has never been investigated in interstitial diseases, but it is up-regulated in the serum of patients with Nonalcoholic fatty liver disease (NAFLD) that may lead to the development of liver cirrhosis and fibrosis." (PMID 38322285, 2023).
lung carcinoma (1 paper, 2018). "In conclusion, our findings suggest that LCP1 may represent a novel peptide that binds specifically to lung cancer cells and further studies can pave the way for its application as a potential targeting moiety in the targeted delivery of diagnostic and therapeutic agents into lung malignant cells." (PMID 29755570, 2018).
lymphopenia (1 paper, 2024). Reduction in the number of lymphocytes. "CyTOF analysis revealed higher immune cell counts in these peripheral locations in the LCP1 knockdown group compared to the control group, further emphasizing the potential protective role against lymphopenia, which is associated with immunodepression, played by decreased levels of LCP1 in MoDMs." (PMID 38164159, 2024).
myeloid leukemia (1 paper, 2022). A clonal proliferation of myeloid cells and their precursors in the bone marrow, peripheral blood, and spleen. "As LCP1 broadly expressed in all hematopoietic cells and HCK has been reported in myeloid leukemia, these two genes were not included in the following analysis." (PMID 35771283, 2022).
nephritis (1 paper, 2024). Inflammation of renal tissue. "Using pharmacovigilance and multi-omic data, a bivariate regression model of lymphocyte cytosolic protein 1 (LCP1) and adenosine diphosphate-dependent glucokinase (ADPGK) was developed to predict immune-mediated reactions in patients treated with ICPI, including nephritis." (PMID 39654653, 2024).
non-alcoholic fatty liver disease (1 paper, 2022). "In a genome-wide association study (GWAS), LCP1 was associated with non-alcoholic fatty liver disease." (PMID 35600488, 2022).
parasitemia (1 paper, 2012). "LCP3 also conferred a significant reduction in liver-stage parasite burden and blood-stage parasitemia; whereas LCP1 and LCP2 conferred protection against liver-stage parasite burden only." (PMID 22936972, 2012).
pulpitis (1 paper, 2021). Inflammation of the dental pulp. "Given this evidence, it can be assumed that LCP1 might be involved in the pathogenic mechanism of pulpitis by regulating T cell-mediated immune response." (PMID 33777260, 2021).
sarcoma (1 paper, 2024). A usually aggressive malignant neoplasm of the soft tissue or bone. "Collectively, these data propose LCP1 as a candidate driver of cancer progression in sarcomas and a target for future drug development." (PMID 38810090, 2024).
schizophrenia (1 paper, 2024). A major psychotic disorder characterized by abnormalities in the perception or expression of reality. "A rare LCP1 missense variant has also been associated with schizophrenia in the Ashkenazi Jewish population." (PMID 38422004, 2024).
scoliosis (1 paper, 2024). A congenital or acquired spinal deformity characterized by lateral curvature of the spine. "NACET treatment reduces scoliosis penetrance and severity in rpgrip1l-/- and decreases astrogliosis and LCP1 + cell number at SCO level." (PMID 39388365, 2024). "Surprisingly, scoliotic rpgrip1l-/- fish showed similar LCP1+ cell number as control fish in the tectum, suggesting a transient increase of macrophage/microglia activation preceding scoliosis." (PMID 39388365, 2024).
Sepsis (1 paper, 2023). Sepsis is defined as life-threatening organ dysfunction caused by a dysregulated host response to infection. "Four proteins showed a >3-fold difference between HLH and sepsis: actin, cytoplasmic 1 (ACTB); actin, cytoplasmic 2 (ACTG1); CD16a antigen (FCGR3A); and plastin-2 (LCP1)." (PMID 37653176, 2023).
steatosis (1 paper, 2023). Increased lipid within the cytoplasm of cells. "LCP1 gene was the most associated gene with steatosis grade (r = 0.46, p = 1.16 × 10-3) and the lobular inflammation grade (r = 0.32, p = 3.06 × 10-2)." (PMID 37008925, 2023).
synovitis (1 paper, 2021). Inflammation of a synovial membrane. "Except for LCP1, CTSZ and PTPRC, all proteins have never been described in human synovitis." (PMID 35008858, 2021).
uremia (1 paper, 2023). A clinical syndrome associated with the retention of renal waste products or uremic toxins in the blood. "The current study systematically identified three candidate hub genes (FGR, LCP1, and C5AR1) and established a nomogram to assist in diagnosing USCP with uremia using various bioinformatic analyses and machine learning algorithms." (PMID 36823662, 2023). "Our study systematically identified three candidate hub genes (FGR, LCP1, and C5AR1) and established a nomogram to assist in the diagnosis of USCP with uremia using various bioinformatic analyses and machine learning algorithms." (PMID 36823662, 2023).
viral infection (1 paper, 2021). "AutoAgs such as LCP1 and NACA that are altered in the T cells of COVID patients may provide insight into T-cell responses in the viral infection and merit further study." (PMID 34729561, 2021).
cancer (60 papers, 2009 to 2026). A tumor composed of atypical neoplastic, often pleomorphic cells that invade other tissues. "The association of LCP1 with immune system has sparked interest in its potential as a biomarker for cancer diagnosis and prognosis." (PMID 38977952, 2024). "The silencing of LCP1 by siRNA suppressed both cancer cell growth and metastatic phenotypes, and LCP1-positive OSCC cases were closely associated with the tumor size and regional metastasis." (PMID 33723306, 2021). "Among the L- and T-isoforms of plastins, LCP1 is the L-isoform of plastin that has been found in many malignant tumors, suggesting an association of its expression with tumorigenesis." (PMID 32992891, 2020). "Two of 15 ONP cancers (13%) exhibited relatively greater expression of mpx1 versus lcp1, indicating a predominance of neutrophils." (PMID 39511408, 2025). "LCP1 levels were at least 3-fold higher in 4 primary cancer tissues (#1, #2, #3, and #6) compared to their adjacent noncancerous counterparts, and its expression was elevated in all recurrent cancer tissues relative to the corresponding noncancerous epithelia." (PMID 41044643, 2025). "In these 13 cancers, lcp1-positive cells were frequently located along the periphery and invasive margins." (PMID 39511408, 2025). "In OSCC, elevated LCP1 expression has been observed in cancer tissues and is positively correlated with lymphatic metastasis." (PMID 41044643, 2025). "In these two cancers, mpx1-positive cells were present primarily within the tumor, while lcp1-positive cells were more abundant at the tumor periphery, and there was limited overlap of cells expressing these markers in serial sections." (PMID 39511408, 2025). "We further assessed LCP1 Gene expression in pretreatment cancer tissues from 224 OSCC patients using qRT-PCR." (PMID 41044643, 2025). "In the current study, we observed limited overlap of lcp1- and mpx1-expressing cells in serial sections of ONP cancers, suggesting that most lcp1-positive cells in these specimens are macrophages." (PMID 39511408, 2025). "The effectors of migration and apoptosis in other cancers and developing tissues were differentially expressed: LCP1 and CXCL5 were upregulated, while PROSER2 and PCDHA6 were downregulated." (PMID 40323130, 2025). "The abnormal expression of lymphocyte cytosolic protein 1 (LCP1) is closely related to various cancer stages and severity." (PMID 38200523, 2024). "LCP1 is a cytoskeletal protein that has been shown to directly interact with multiple integrins and is important in cell adhesion and migration in cancer cells." (PMID 38810090, 2024). "Here, LCP1, PRDX2, OGN and, TAGLN2 together with other molecular interactors, linked with highest hits, according to KEGG database, to pathways in cancer, PI3K-AKT and MAPK signaling pathways." (PMID 38322285, 2023). "Among them, LCP1 was expressed in hematopoietic cellular lineages and many types of cancers, which regulated the cell movement by interacting with actin and plays a key role in the process of cell migration." (PMID 36574182, 2023). "Further study is required to investigate if ENX is the upstream molecule of LCP1 in the cancer cells." (PMID 28230172, 2017). "LCP1 has been reported to be involved in tumorigenesis and progression across various cancer types." (PMID 40740857, 2025). "Three plastin isoforms are expressed in vertebrates: PLS1 (I-plastin) is expressed in absorptive intestinal and kidney cells, PLS2 (LCP, LCP1, or L-plastin) is predominantly found in hematopoietic and cancer cells, while PLS3 (T-plastin) is ubiquitously expressed in all solid tissues." (PMID 37484945, 2023). "For example, LCP1 increased the resistance of cancer cells to apoptosis." (PMID 35600488, 2022). "Interestingly, dual inhibition of ABCE1 and LCP1 resulted in an additive effect on cancer cell migration, invasion, and proliferation." (PMID 31007850, 2019).